DCAF4 (DDB1 and CUL4 associated factor 4)
Description:
May function as a substrate receptor for CUL4-DDB1 E3 ubiquitin-protein ligase complex.
Synonyms: WDR21; WDR21A; DKFZp434K114
Tractability: PROTAC: ubiquitination databases record sites on it.
Gene: Protein-coding gene on chromosome 14 (72,926,358 to 72,962,098, forward strand). Ensembl gene ENSG00000119599.
Subcellular location (Human Protein Atlas): Nucleoplasm
Pathways (Reactome):
Metabolism of proteins: Neddylation
Gene Ontology:
Molecular function: protein binding
Biological process: cell population proliferation; protein ubiquitination
Cellular component: Cul4-RING E3 ubiquitin ligase complex; Cul4A-RING E3 ubiquitin ligase complex; Cul4B-RING E3 ubiquitin ligase complex; nucleoplasm
Genetic constraint (gnomAD): Loss-of-function variants: 39 observed, 64.73 expected, observed/expected ratio (o/e) 0.6, 90% interval 0.47 to 0.79. The upper end of that interval is the gene's LOEUF score, 0.79, which puts it in group 3 of 6, group 1 being the genes least tolerant of losing a copy. Missense variants: 577 observed, 676.42 expected, observed/expected ratio (o/e) 0.85, 90% interval 0.8 to 0.91. Synonymous variants: 243 observed, 266.72 expected, observed/expected ratio (o/e) 0.91, 90% interval 0.82 to 1.01.
Homologues: Orthologues: chimpanzee DCAF4 (99% identical), macaque DCAF4 (97% identical), dog DCAF4 (87% identical), rat Dcaf4 (82% identical), mouse Dcaf4 (81% identical). Paralogues in human: DCAF4L1 (61% identical), DCAF4L2 (59% identical), MAPKBP1 (16% identical), WDR62 (15% identical), AHI1 (14% identical), WDR75 (14% identical), TEP1 (14% identical), WDR7 (13% identical), WDR27 (13% identical), WDR81 (13% identical), POC1A (12% identical), SNRNP40 (12% identical), and 14 more.
Diseases named in the same sentence as DCAF4 in open-access papers:
DCAF4 is named in the same sentence as 9 diseases in open-access papers, as found by Europe PMC text mining. Sharing a sentence is not in itself a finding about the gene and the disease. The quoted sentences say what the papers report.
lung adenocarcinoma (2 papers, 2017 to 2026). A carcinoma that arises from the lung and is characterized by the presence of malignant glandular epithelial cells. "Analysis of The Cancer Genome Atlas (TCGA) data revealed that seven DCAF genes (DCAF2, DCAF4, DCAF7, DCAF12, DCAF13, DCAF15, and DCAF17) were significantly upregulated in lung adenocarcinoma (LUAD)." (PMID 41047465, 2026). "Here we infer the potential impact of 19 well-defined DCAFs in human lung adenocarcinomas (LuADCs) using integrative omics analyses, and discover that mRNA levels of DTL, DCAF4, 12 and 13 are consistently elevated whereas VBRBP is reduced in LuADCs compared to normal lung tissues." (PMID 28336923, 2017).
Alzheimer disease (1 paper, 2015). A progressive, neurodegenerative disease characterized by loss of function and death of nerve cells in several areas of the brain leading to loss of cognitive function such as memory and language. "Mutations in DCAF4 are associated with leucocyte telomere length, and there is evidence that shortened telomere length in leucocytes is associated with other neurodegenerative diseases, such as Parkinson and Alzheimer’s disease." (PMID 26550040, 2015).
osteosarcoma (1 paper, 2017). A usually aggressive malignant bone-forming mesenchymal neoplasm, predominantly affecting adolescents and young adults. "DCAF11, instead of DCAF4, was significantly induced in U2OS, MG63, Saos-2 and HOS osteosarcoma cell lines compared with hFOB1.19 cells." (PMID 28446751, 2017). "To confirm this hypothesis, we examined DCAF4 and DCAF11 protein levels in different osteosarcoma cell lines." (PMID 28446751, 2017). "The CUL4B-Flag immunocomplex from hFOB1.19, U2OS or Saos-2 cells pulled down DCAF4 and DCAF11, but not DCAF1, 8 and 15, indicating that these two DCAFs form complexes with CUL4 and DDB1 in osteosarcoma cells." (PMID 28446751, 2017).
cancer (1 paper, 2022). A tumor composed of atypical neoplastic, often pleomorphic cells that invade other tissues. "Interestingly, the expression patterns of DCAF4, COX10, and TGOLN2 presented the best tool set to identify and separate cell lines with their respective irinotecan-resistant variants from other pairs of parental–resistant CRC cells lines that were delivered from different cancer locations or stages." (PMID 35885025, 2022).
tumor (1 paper, 2021). "However, as we found a relative downregulation of DCAF4 in nearly all withinSVZ-samples, the relevance of this observation compared to increased expression of gene sets involved in (epithelial-) mesenchymal transition in tumor samples from the SVZ region remains unclear." (PMID 34359668, 2021).
DCAF4 also shares sentences with these, for which no sentence is quoted: colorectal cancer (1 paper); lung carcinoma (1); myasthenia gravis (1); neurodegenerative disease (1).